ENSG00000293606 (novel protein, readthrough between SLC5A3 and MRPS6)
Gene: Protein-coding gene on chromosome 21 (34,073,576 to 34,143,030, forward strand). Ensembl gene ENSG00000293606.
Homologues: Orthologues: dog SLC5A3 (84% identical), rabbit SLC5A3 (80% identical), zebrafish slc5a3b (57% identical), zebrafish slc5a3a (53% identical), Drosophila melanogaster CG33124 (13% identical), Drosophila melanogaster CG31668 (13% identical), Drosophila melanogaster bumpel (12% identical), Drosophila melanogaster CG31262 (12% identical), Drosophila melanogaster kumpel (12% identical), Drosophila melanogaster CG2187 (12% identical), Drosophila melanogaster SLC5A11 (12% identical), Drosophila melanogaster rumpel (12% identical), and 2 more. Paralogues in human: SLC5A3 (86% identical), SLC5A9 (40% identical), SLC5A11 (39% identical), SLC5A1 (39% identical), SLC5A2 (38% identical), SLC5A4 (35% identical), SLC5A10 (35% identical), SLC5A12 (16% identical), SLC5A8 (16% identical), SLC5A6 (15% identical), SLC5A5 (15% identical), SLC5A7 (12% identical).